Y_RNA (Y RNA )
Gene: Miscellaneous RNA gene on chromosome 4 (75,662,120 to 75,662,213, reverse strand). Ensembl gene ENSG00000201644.
Homologues: Orthologues: chimpanzee Y_RNA (99% identical). Paralogues in human: RNY4 (87% identical), RNY4P10 (86% identical), RNY4P14 (86% identical), Y_RNA (86% identical), RNY4P25 (85% identical), RNY4P6 (84% identical), Y_RNA (84% identical), RNY4P13 (83% identical), RNY4P3 (83% identical), RNY4P7 (83% identical), Y_RNA (83% identical), RNY4P34 (82% identical), and 85 more.